INS (insulin)
Diseases named in the same sentence as INS in open-access papers (continued):
Sharing a sentence is not in itself a finding about the gene and the disease.
diabetes (continued). "The role of IAs in diabetes treatment is controversial, but they may inhibit the interaction between insulin and its receptor and thereby cause hyperglycaemia." (PMID 35742925, 2022). "On the contrary, cholesterol-lowering drugs or genetic variants could impair glucose homeostasis and lead to diabetes by decreasing pancreatic β-cell insulin secretion or inducing insulin resistance of skeletal muscle cells, adipocytes, or hepatocytes." (PMID 35571202, 2022). "Because of the risk of hypoglycemia, insulin and other medications used to treat diabetes may need dose adjustment." (PMID 35329847, 2022). "Furthermore, the same study showed that lower adipose tissue of ACE2 was associated with diabetes, obesity status, BMI and increased insulin and triglyceride levels." (PMID 35807129, 2022). "Defective insulin processing is associated with obesity and diabetes." (PMID 35963866, 2022). "Diabetes is caused by a fault in the insulin production of the body and has different types." (PMID 36501537, 2022). "Moreover, extrinsic factors, such as hypoglycemia caused by treatment, diabetes peripheral neuropathy, muscle weakness, visual impairment, and some hypoglycemic agents including thiazolidinediones, SGLT2i, and insulin, also increase the fracture risk." (PMID 36120431, 2022). "Type 2 diabetes mellitus risk genes can lead to impaired insulin signaling." (PMID 36185474, 2022). "Diabetes refers to a hyperglycemic condition that may be caused either by a deficiency of insulin or defects in its action or both." (PMID 35707783, 2022). "Insulin signaling and diabetes have been extensively implicated in AD and neurodegeneration." (PMID 36389068, 2022). "In addition, common variants in this gene were also associated with diabetes-related risk metabolic traits, such as raised fasting glucose, insulin and triglycerides, and lower HDL-C31." (PMID 36376549, 2022). "According to the fetal insulin hypothesis, polymorphisms influencing glucose metabolism (and thus later diabetes) are also associated with impaired fetal growth, through the actions of insulin." (PMID 35951032, 2022). "Diabetes mellitus (DM) is an endocrine disease caused by chronic hyperglycemia associated with a relative or absolute insulin deficiency, i.e., there can be a defect in insulin secretion, its action (insulin resistance), or both." (PMID 35956932, 2022). "Diabetes mellitus is characterized by a state of chronic hyperglycemia associated with alterations in carbohydrate, fat, and protein metabolism leading to a deficit of insulin secretion and to insulin resistance, which are involved in muscle protein loss." (PMID 35886528, 2022). "However, these human native insulin products share the risk of late postprandial hypoglycemia and variable glucose-reducing profiles, which can be a major barrier for effective diabetes management." (PMID 35890301, 2022). "Sacubitril/valsartan reduced HbA1c and new insulin therapy in patients with heart failure and diabetes across the spectrum of LVEF but may be associated with a slightly higher risk for hypoglycemia." (PMID 35717169, 2022). "Several genetic disorders lead to the development of diabetes, such as maturity-onset diabetes of the young, caused by genetic defects of β-cell function, genetic defects in insulin action genetic syndromes, including Down syndrome and Klinefelter syndrome, among many others." (PMID 36671612, 2022). "The development of diabetes involves multiple pathogenic processes, including autoimmune destruction of pancreatic B cells and subsequent insulin deficiency, as well as abnormalities that lead to resistance to insulin action." (PMID 35030973, 2022). "Furthermore, intensive insulin therapy is known to sustain endogenous insulin secretion, lower the risk for hypoglycemia, and reduce diabetes complications in T1DM patients." (PMID 35518934, 2022).
diabetes (continued). "Hyperactivation of mTORC1 due to chronic conditions, such as chronic high glucose exposure or diabetes, or overexpression of any one of the components of the mTORC1 complex leads to the destruction of β-islet cells, insulin resistance, loss of glucose homeostasis, and obesity." (PMID 35672290, 2022). "The discovery of insulin and its uses are linked to the beginning of diabetes treatment." (PMID 36381916, 2022). "In another systematic review and meta-analysis of double-blind RCTs, the authors evaluated that Mg supplementation appears to have a beneficial influence on glucose parameters in people with DM2 and insulin sensitivity parameters in people at high risk of diabetes." (PMID 35565682, 2022). "Insulin treatment was associated with other characteristics generally associated with high cardiovascular risk, including prior myocardial infarction, coronary revascularization, and heart failure and longer duration of diabetes." (PMID 34158057, 2021). "Type 1 diabetes mellitus (DM1) responds to a multifactorial pathogenesis essentially linked to an autoimmune aggression mediated by autoantibodies that generates a progressive loss of insulin-producing β-cells in the pancreas." (PMID 34830663, 2021). "Type 1 diabetes mellitus (T1D), also known as juvenile-onset diabetes, is caused by T-cell-mediated autoimmune attack of pancreatic islet β-cells, leading to the islet failure to produce insulin." (PMID 33478120, 2021). "The injection of insulin also caused mild discomfort in diabetes patients." (PMID 34732146, 2021). "Diabetes has inevitable detrimental effects on the quality of life, including issues with psychological and physiological functioning, risk of developing comorbidities, and the financial burden of insulin treatment." (PMID 34940233, 2021). "Type-1 (T1DM) and type-2 (T2DM) diabetes mellitus (DM) are metabolic disorders associated with hyperglycaemia and changes in insulin production and signalling.102−104 T1DM is characterized by the loss of insulin-producing β-islet cells in the pancreas and deficient insulin generation." (PMID 33723575, 2021). "Furthermore, as the risk factors of TLF in this cohort, insulin‐treated diabetes, hemodialysis, peripheral vascular disease, and in‐stent restenosis were those of clinically indicated TLR." (PMID 34522790, 2021). "Duration of diabetes confounded the association of currently taking insulin negatively." (PMID 33651277, 2021). "Because β-adrenoceptor agonists can influence glucose homeostasis by modulating insulin secretion, liver metabolism, and uptake of glucose into muscle, these results could be partly explained by poorly controlled diabetes, which would increase the risk of PD." (PMID 34684044, 2021). "The essential roles of adipocytokines vis-a-vis satiety, appetite, regulation of fat storage and energy, glucose tolerance, and insulin release, solidifies adipose tissue role in the development and pathogenesis of diabetes mellitus and the complications associated with the disease." (PMID 34299261, 2021). "The two common types of diabetes include Type 1, arising from the inability of the pancreatic β-cells to produce insulin, and Type 2, which is caused by insulin resistance and/or insufficient insulin production." (PMID 34203366, 2021). "Similarly, we observed associations between reduced insulin sensitivity and higher prevalences of cognitive impairment, hypertension, diabetes, dyslipidemia, and cardiovascular disease." (PMID 34702849, 2021). "pNDRG1-T346 in adipose tissue may serve as a marker of diabetes-associated impairments of the systemic incretin profile and insulin sensitivity." (PMID 34956089, 2021). "Using C-peptide and HDL-cholesterol instead of HOMA2-B and HOMA2-IR, three of the clusters mapped with high sensitivity (80.6–90.7%) to the previously identified severe insulin-deficient diabetes (SIDD), severe insulin-resistant diabetes (SIRD) and mild obesity-related diabetes (MOD) clusters." (PMID 34110439, 2021).
diabetes (continued). "Thus, based on the ARTFOOD trial data, this secondary analysis of a randomized trial investigates the effect of LNS on glucose metabolism and insulin function as indicators of diabetes risk in people with HIV with compromised immunity." (PMID 34657634, 2021). "Poor metabolic control may lead to long-term diabetes-related complications, and insulin restriction is associated with a threefold increase in mortality rates." (PMID 34638531, 2021). "Beneficial effects of intranasal insulin administration have been shown in clinical trials of its use to improve memory and cognition, and to reduce the memory loss caused by Alzheimer’s disease and diabetes." (PMID 35002636, 2021). "Diabetes autoimmunity was confirmed in patients with this association and, in comparison with T1D controls, patients with T1D+DS developed diabetes earlier, used a lower insulin dose and achieved better metabolic control." (PMID 33939908, 2021). "Most of the interest in CFTR modulator therapy in CFRD has focused on potential benefit, including whether it might prevent or delay onset of diabetes if started early enough in life, improve insulin secretion, and/or reduce CFRD-associated mortality." (PMID 34926166, 2021). "Interestingly, different studies have shown that some miRNAs are associated with glucose homeostasis, mostly in association with genes for diabetes-relevant pathways like insulin signaling." (PMID 33670401, 2021). "However, in a rodent model of insulin-deficient diabetes, we showed that intraperitoneal insulin led to a decrease in 11β-HSD1 activity in the liver, whereas subcutaneous insulin did not." (PMID 34970219, 2021). "Diabetes mellitus is characterized by a chronic hyperglycemic condition possibly induced by insulin deficiency, damage to insulin signaling, or non-autoimmune etiology or caused by a remarkably diminished insulin sensitivity." (PMID 34475822, 2021). "However, we believe that these findings contribute to a better understanding of the association of the pandemic with insulin treatment for diabetes." (PMID 34730822, 2021). "In a cross-sectional analysis of 3690 diabetes-free women from the Nurses Health Study, Lay and colleagues also found total, unprocessed and processed RM intakes to be associated with higher Hb A1c and plasma insulin concentrations." (PMID 33554272, 2021). "Previous studies have shown that GNPNAT1 is associated with insulin secretion and diabetes." (PMID 33661921, 2021). "Additionally, numerous studies have found that younger age, medication use (oral medicine and/or insulin injection), and longer duration of diabetics strongly associate with DN." (PMID 33897777, 2021). "Furthermore, exosomal circular RNAs (circRNAs) have also been associated with diabetes progression by decreasing β-cell proliferation and insulin secretion." (PMID 34959338, 2021). "Diabetes is part of metabolic diseases and is characterized by high blood sugar levels over a prolonged period as result of an insulin-deficient production or an inappropriate response to insulin by our cells." (PMID 34589130, 2021). "However, the MafA deficient mice developed diabetes postnatally, suggesting that MafA regulates maturation and is required for glucose-responsive expression of insulin in adult β cells." (PMID 34882233, 2021). "All eight of the diabetes-associated OTUs were also significantly associated with insulin and hypoglycemic drugs, suggesting that drug intake may influence the diabetes signal, as the microbiome is known to interact with pharmaceuticals." (PMID 34915914, 2021). "The reduction of PC and lysoPC in PCOS-b may indicate an increased risk of insulin resistance and diabetes mellitus, which was consistent with our previous study that found aberrant insulin metabolism in PCOS-b." (PMID 34434168, 2021).
diabetes (continued). "Magnesium deficiency can affect insulin regulation and may increase the risk of diabetes due to its essential role in the activation of the tyrosine kinase enzyme for insulin receptor activity." (PMID 34836395, 2021). "Additionally, insulin resistance in target tissues and a relative deficiency of insulin secretion from pancreatic β-cells are the major metabolic issue with diabetes." (PMID 34641501, 2021). "Longer disease duration may be associated with a higher number and more serious diabetes-related complications and with longer insulin use." (PMID 33776906, 2021). "Leptin is associated with metabolism, insulin sensitivity, and diabetes." (PMID 34446063, 2021). "Materials and Methods: A prospective cohort study was conducted via an Electronic Medical Record search for patients attending the Virginia Commonwealth University Medical Weight Loss Program from 2014 to 2020 with Type 2 Diabetes Mellitus who initially presented on insulin." (PMID 34458301, 2021). "In diabetes, loss of insulin-producing pancreatic beta-cell mass, is accompanied by dysfunction of glucagon-producing alpha cells, which fail to respond to the normal suppressive effects of glucose and insulin, leading to hyperglucagonaemia." (PMID 34081167, 2021). "An increased insulin requirement in patients with T1DM and consequently a loss of insulin sensitivity towards exogenous insulin can lead to a phenotype similar to that of subjects with type 2 diabetes mellitus (T2DM) predisposing them to adipose tissue dysfunction." (PMID 33099763, 2021). "In this study, we used ZDF rats to successfully address the hypothesis that imeglimin, a novel therapeutic agent, could ameliorate the loss of insulin secretory capacity and β‐cell mass in the context of severe diabetes." (PMID 33855202, 2021). "The term “diabetes” as defined by the American Diabetes Association (ADA) is a group of metabolic diseases characterized by chronic hyperglycemia resulting from disturbances in insulin secretion and/or function." (PMID 34830017, 2021). "These emerging patterns of association are consistent with the heterogeneous birthweight effects of monogenic causes of diabetes secondary to reduced insulin secretion and suggest that different susceptibility loci exert their effects on beta cell function at different stages in the life course." (PMID 33569631, 2021). "The average specific activity of Na, K -ATPase in healthy people is higher than among people with diabetes in the same age and the same gender, which may be associated with insulin levels." (PMID 34203167, 2021). "β-cell dedifferentiation and dysfunction under insulin-resistant conditions cause hyperglycemia, which would in turn promote further β-cell dedifferentiation, activating a vicious circle that will eventually lead to frank diabetes." (PMID 33921851, 2021). "Later, Cerasi and Luft used IV glucose infusion tests and computer modeling to identify an insufficient insulin response to glucose as a characteristic of diabetic individuals, concluding that this loss of insulin secretion was likely a “prerequisite” for diabetes." (PMID 34822454, 2021). "Diabetes mellitus is a chronic endocrine metabolic disorder that takes place because of absolute or partially deficient insulin secretory response by pancreatic cells or sometimes due to developed insulin resistance by the body." (PMID 34912223, 2021). "In order to reduce the serious consequences caused by diabetes and hyperglycemia, continuous monitoring of blood glucose concentration should be used, especially by those who manage blood glucose levels with insulin, requiring manual injections or the use of insulin pumps." (PMID 34577473, 2021). "Moreover, PREP1 deficiency induces protection from diabetes, reduces inflammatory responses, and increases insulin sensitivity in adipose tissue." (PMID 34327205, 2021).
diabetes (continued). "Diabetes mellitus is a long-term metabolic disorder characterized by elevated blood glucose concentration that results from absolute insulin deficiency or insufficient insulin secretion and/or insulin sensitivity." (PMID 33467194, 2021). "In order to avoid Type 2 Diabetes Mellitus and other complications of the metabolic disease, these delicate functions are highly regulated, and their defects can therefore cause impaired insulin secretion." (PMID 33557754, 2021). "Although environmental causes that drove this positive selection remain unknown, studies had identified variants associated with type 2 diabetes mellitus, insulin secretion, body mass index, obesity, and adiposity, when admixture was considered." (PMID 33841501, 2021). "The need for a lower dose of insulin, associated with better glycemic control, suggests that diabetes in people with DS may be associated with less beta-cell function loss." (PMID 33939908, 2021). "Protein hydrolysates and peptides from cereals and pseudocereals have been shown to inhibit enzymes associated with diabetes and could maintain glucose homeostasis by improving insulin sensitivity." (PMID 34445765, 2021). "Mitochondrial capacity is considered a good indicator of insulin sensitivity, whereas the excessive glucose exposure or nutrient stress that occur in obesity and diabetes are associated with impaired glucose oxidation, reduced mitochondrial contents, and lowered rates of oxidative phosphorylation." (PMID 34439482, 2021). "For understanding the potential association of gender, age, diet, glycated hemoglobin, insulin use, alcohol consumption, statin use, duration of diabetes and formal education with MCI in T2DM patients, we have performed binomial backward logistic regression analysis." (PMID 35035379, 2021). "Excess adiposity may increase the risk of type 2 diabetes mellitus and cardiovascular diseases by increasing fasting glucose, insulin, and triglyceride levels; raising blood pressure; and promoting systemic inflammation." (PMID 34906131, 2021). "Other diseases associated with obesity, such as brain dysfunction, cancer, and diabetes, may cause dysfunction because of an inability to use glucose, excessive reliance on glucose, or poor insulin signaling." (PMID 34631141, 2021). "ER stress is a central molecular element linked to insulin dysfunction in obesity and diabetes." (PMID 34299638, 2021). "An increased number of smaller adipocytes may link Adcy5 knockout to the previously reported effects on longevity and reduced diabetes risk, because small adipocytes are strongly related to BMI-independent retained insulin sensitivity." (PMID 33919448, 2021). "Current findings are inconclusive as to whether IN insulin can solely treat dementia caused by Alzheimer's disease or MCI in people with diabetes." (PMID 34540446, 2021). "Another report has shown that glucose deficiency in the brain leads to tau pathology and synaptic dysfunction, indirectly suggesting that lower brain glucose levels caused by lower insulin levels in diabetes mellitus may also lead to tau pathology." (PMID 33967937, 2021). "Type 2 Diabetes Mellitus (DM) is a common metabolic disorder characterized by hyperglycemia caused by various factors including impaired insulin secretion, insulin resistance, decreased glucose utilization, excessive hepatic glucose production, and systemic low-grade inflammation." (PMID 33531076, 2021). "The biogenesis and transport of vesicular cargo proteins such as insulin are critical for the maintenance of blood glucose homeostasis, and defects in the trafficking of the vesicular cargo proteins are linked to the onset of diabetes disease." (PMID 34848728, 2021). "Diabetes mellitus (DM) is a metabolic disorder characterized by an elevated level of glucose (hyperglycemia) and disturbance of fat, protein, and carbohydrate metabolism caused mainly by the inability to produce or to utilize insulin." (PMID 33983514, 2021).